KIF18A (kinesin family member 18A)
Diseases named in the same sentence as KIF18A in open-access papers (continued):
Sharing a sentence is not in itself a finding about the gene and the disease.
cancer (continued). "Furthermore, the Broad DepMap cancer database reports that KIF18A dependency is not readily predicted by expression, lineage, or mutational datasets, reinforcing the need for a mechanistic understanding of KIF18A dependency." (PMID 38279026, 2024). "Other authors describe NEK2, MACC1, REG1A, KIF18A, RET, and TIP60 as possible PM-related cancer genes." (PMID 37629011, 2023). "We used multiple public databases such as TIMER, The Cancer Genome Atlas (TCGA), Genotype-Tissue Expression (GTEx), and Human Protein Atlas (HPA) to explore KIF18A mRNA expression in 33 tumors." (PMID 36830695, 2023). "Thus, KIF18A might be a potential therapeutic target for the treatment of cancer." (PMID 32253833, 2020). "The cytotoxic activity of the phenanthrenes in a variety of human cancer cells is attributed by these findings to post translational modifications of NuMA and kinesins HSET/kifC1 and kif18A." (PMID 28209915, 2017). "KIF18A is an essential cytoskeletal motor protein for cell division in CIN+ cancer cells, but it is not necessary for cell division in normal cells." (PMID 41369352, 2025). "In the PJ34-treated cancer cells, the unclustering of NuMA in spindle poles was accompanied by the interference of PJ34 with NuMA binding to α-tubulin and to kinesins HSET/KifC1 and Kif18A that interact with αβ-tubulin." (PMID 40681496, 2025). "KIF18A and KIF23 are members of the kinesin family and were overexpressed in many malignant tumors." (PMID 40255404, 2025). "KIF18A, with elevated mRNA expression in 216 HCC samples paired with para-carcinoma tissues measured by RT-qPCR, was found to be significantly correlated with serum AFP, tumor size, TNM stage, and portal vein tumor thrombus (PVTT), indicating the possible efficiency of KIF18A in HCC diagnosis." (PMID 38433242, 2024). "Our finding that KIF18A, the SAC and PLK1 are highly interdependent suggests that PLK1 may also be a target of choice in cancers with complex karyotypes." (PMID 37639469, 2023). "Although the effect of KIF18A in pan-cancer was described, some limitations should not be overlooked." (PMID 36830695, 2023). "KIF18A expression had a positive or negative correlation with stromal score or immune score in some cancers." (PMID 36830695, 2023). "It is important to note that the HCT-116 WGD+ clones did not display higher KIF18 expression compared to diploid HCT-116 cells, whereas tetraploid MCF10A cells and many WGD+ human cancers expressed higher levels of KIF18A compared to near-diploid cells and WGD− cancers." (PMID 37576603, 2023). "Moreover, we found that KIF18A had a positive correlation with immune checkpoints, such as PD-1, PD-L1, CTLA4, TIGIT, LAG3, HAVCR2, and PDCD1LG2 in a great many cancers." (PMID 36830695, 2023). "In addition, we discovered that KIF18A participated in the cell cycle at the single-cell level and GSEA analysis for most cancers." (PMID 36830695, 2023). "The contribution of TMEM158, KIF18A, and SLC39A1 to cell proliferation or cancer progression was established already, but how exactly they integrate in the YAP signaling pathway is currently unknown." (PMID 33514403, 2021). "Moreover, Oncomine analysis of cancer vs. normal tissue showed that ANLN and KIF18A were highly expressed in multiple HCC datasets." (PMID 31392101, 2019). "As de-regulation of Kif18A plays critical roles in tumor progression, the SUMO regulatory network may be a potential target for cancer intervention." (PMID 25884224, 2015). "Kinesins HSET/kifC1 and kif18A have already been examined for their possible role in cancer therapy, while to the best of our knowledge, NuMA clustering in the spindle poles has not been examined before as a target for cancer cells’ eradication." (PMID 40681496, 2025).
cancer (continued). "To investigate the antiproliferative effects of our KIF18A inhibitors more broadly, we conducted a PRISM (profiling relative inhibition simultaneously in mixtures) screen with AM-1882 on a large panel of DNA-barcoded cancer cell lines, using a 5-d cell growth assay." (PMID 38151625, 2024). "The depletion of KIF18A showed a trend toward increased cyclin B1 (G2M marker) and cl-PARP (apoptosis marker) protein levels as well as decreased MCL-1 (a pro-survival marker) protein levels in those cancer cell lines sensitive to KIF18A KD in our cell growth assay." (PMID 38151625, 2024). "Secondly, our study did not investigate the molecular mechanism of KIF18A in cancers." (PMID 36830695, 2023). "Ideal targets are kinesins whose expression is largely restricted to cancer cells and/or whose function is dispensable in non-malignant cells, as has been described for KIF20A, KIFC1, and KIF18A." (PMID 40002279, 2025). "While KIF18A expression is low in non-malignant tissues, elevated KIF18A expression has been detected at both RNA and protein levels in NSCLC tissues, consistent with reports for several other human cancers." (PMID 40002279, 2025). "Furthermore, while a functional genetic interaction between YAP and TRAM2, KIF18A, TMEM158, and SLC39A1 was never reported, the role of TMEM158, KIF18A, and SLC39A1 in cell proliferation or cancer progression was already established before." (PMID 33514403, 2021).
tumor (46 papers, 2012 to 2026). "In BC, KIF18A expression levels are increased and associated with higher tumour grade, metastases and shorter survival." (PMID 38264947, 2024). "Mismatched expression of KIF18A in MCF-7 cells leads to a multinucleus formation associated with tumor emergence." (PMID 35464837, 2022). "The antiproliferative effects of KIF18A loss in CIN tumor cells coincided with a number of mitotic errors, including prolonged mitotic delays, multipolar spindles, and centrosome fragmentation." (PMID 34135330, 2021). "It has been shown that overexpression of Kif18a is associated with tumour grade, development of metastasis and poor survival." (PMID 30961553, 2019). "Kif18A is up-regulated in several types of tumors and its expression is closely associated with the tumor grade, metastasis, and survival." (PMID 25884224, 2015). "Taken together, the identified circRNAs and hub genes, as well as the CBT15_circR_28491-miR-139-3p-Kif18a/Cdca8/Nek2 axis, may be closely linked to the thrombotic risk associated with neoplasia and play essential roles in the progression of DVT." (PMID 40662137, 2025). "The study showed that KIF18A positively correlates with the Ki67 proliferation index, indicating that KIF18A may be associated with the acceleration of tumor cell division." (PMID 39518001, 2024). "Therefore, it is vitally important to discuss the relationship between KIF18A and tumor-associated immune cell infiltration." (PMID 36830695, 2023). "For example, Kif18A is mis-expressed in numerous cancers, which correlates with advanced tumor grade and poor survival, whereas Kif18B has been implicated in tumor progression through Wnt signaling and may be a driver in carcinogenesis." (PMID 30577528, 2018). "High KIF18A RNA and protein expression in NSCLC has been associated with higher tumour stage, tumour differentiation, lymph node metastasis, and tumour mutation burden." (PMID 40002279, 2025). "Mitotic arrest and multipolar spindles in KIF18A-depleted, chromosomally unstable tumor cells strongly correlate with decreased proliferation." (PMID 38410188, 2024). "Kinesin-8 family: KIF18A affected Akt/MMP7/9 signaling with an impact on tumor invasion and migration and CyclinB1-related signaling with an influence on proliferation." (PMID 38433242, 2024). "Apart from SKP2, ITGB4, CDKN3, TFGP1, SLCO1B3, CDX2 and KIF18A, the remaining model genes showed significant correlations with stem cell score, immune score and tumour microenvironment." (PMID 39656479, 2024). "KIF18A is a member of the kinesin-8 family that is tumor-related by regulating microtubule dynamics and mitosis." (PMID 38195458, 2024). "An examination of tumor specimens revealed an escalation in the expression of KIF18A, in conjunction with heightened levels of CENPE, SNHG4, KIAA1841, CDCA2, and PRR11 mRNA." (PMID 38495502, 2024). "Next, we evaluated the efficacy of our KIF18A inhibitors in the near-diploid CIN− CAL-51 CDX tumor model using the same dose and schedule." (PMID 38151625, 2024). "It is presumed that KIF18A interacts with tumor and immune cells, as indicated by its positive correlation with several genes such as PD-L1, PD-1, CTLA4, TIGIT, HAVCR2, PDCD1LG2, and LAG3." (PMID 39518001, 2024). "Genetic ablation of KIF18A led to proliferation inhibition via centrosome fragmentation and mitotic arrest both in vitro and in vivo, primarily affecting tumour cells with chromosome instability while inducing relatively low toxicity in diploid cells." (PMID 38264947, 2024). "First, by analyzing the published data of the expression of TCGA and GEO, we found that the expression of KIF18A gene is increased in tumor tissues." (PMID 37708299, 2023). "A dysfunctional expression of KIF18A results in abnormal sister chromatid segregation during mitosis, resulting in tumor development." (PMID 36830695, 2023).
tumor (continued). "Molecular function (MF) enrichment analysis showed that the role of KIF18A in tumor pathogenesis was related to tubulin binding, microtubule binding, microtubule motor activity, and motor activity." (PMID 36830695, 2023). "Wozniak showed that mitosis in early tumor regulation can lead to malignancy, suggesting that overexpression of KIF18A can lead to poor control of cellular mitosis." (PMID 35464837, 2022). "To further investigate the mechanism underlying differences in survival between the KIF18A-high and KIF18A-low expression groups, we analyzed the correlation between KIF18A expression level and tumour microenvironment." (PMID 35591854, 2022). "We noticed that the tumor volume of the KIF18A ablation group was smaller than that of the control group." (PMID 35464837, 2022). "The KIF18A gene deletes except that it significantly suppresses tumor cell proliferation outside the body." (PMID 35464837, 2022). "Recently, the expression and role of KIF18A in tumours have attracted increasing attention and have become a hotspot in molecular oncology research." (PMID 35591854, 2022). "Consistent with previous work, the magnitude and variance of mitotic delays were larger in KIF18A KD CIN tumor cells than diploid (MCF10A) or near-diploid cells (HCT116) 19–21,24,25." (PMID 33619254, 2021). "Our results demonstrate that the majority of CIN tumor cells tested depend on the kinesin-8 motor KIF18A to maintain bipolar spindle integrity and promote proliferation." (PMID 33619254, 2021). "CIN tumor cells dependent on KIF18A for cellular proliferation also showed a significant increase in multipolar spindle formation and centrosome fragmentation." (PMID 34135330, 2021). "KIF18A is also largely dispensable for the proliferation of diploid somatic cells in vivo but is necessary for tumor growth." (PMID 33619254, 2021). "Undoubtedly, the well-described effects of MYC on global transcription and protein production, CCND1 on cell cycle transition, and KIF18A on chromatin segregation contribute greatly to YAP-mediated in vivo tumor expansion." (PMID 33514403, 2021). "The results showed that the expression of the Kif18A protein was higher by immunohistochemistry in NSCLC tissues than in normal tissues, and was associated with tumor differentiation, lymph node metastasis, and TNM staging." (PMID 31977917, 2020). "The expression of the Kif18A protein by immunohistochemistry was higher in NSCLC tissues than in normal tissues, and was associated with tumor differentiation, lymph node metastasis, and TNM staging." (PMID 31977917, 2020). "In conclusion, the expression of the Kif18A protein by immunohistochemistry was higher in NSCLC tissues than in normal tissues and was associated with tumor differentiation, lymph node metastasis, and TNM staging." (PMID 31977917, 2020). "KIF18A expression levels were found to positively contribute to tumor stage, lymphatic invasion, lymph node metastasis venous invasion, and peritoneal dissemination in CRC." (PMID 31392101, 2019). "The identified gene expression signature included 14 genes, five (CDYL, ATP6V0A4, PREP, RTN41P1, BEND3 and Kif18A) of which were up-regulated in the group of primary tumours of the patients with visceral organ metastasis." (PMID 30961553, 2019). "We compared the grey values of each band, and the KIF18A band in the tumour tissues of six cases was significantly darker than that in adjacent tissues." (PMID 29466986, 2018). "Univariate analysis revealed that high KIF18A expression, median size of tumor ≥5cm, multiple tumor number, III/IV of TNM stage, PVTT and distant metastasis were associated with a shorter DFS." (PMID 25431949, 2014). "It is very interesting that KIF18A high expression, tumor size ≥5cm, and TNM stage III/IV were also identified as independent prognostic factors for DFS and OS by multivariate analysis." (PMID 25431949, 2014). "In addition, small inhibitors targeting KIF18A are particularly effective in tumor cells with CIN feature." (PMID 40175357, 2025).
tumor (continued). "Notably, genomic analyses of TCGA tumours indicate that a high proportion of LUAD (59%) and LUSC (64%) exhibit WGD and signatures of CIN, implicating their susceptibility to KIF18A- and Eg5-targeted drugs." (PMID 40002279, 2025). "Furthermore, high KIF18A H score values showed a significant direct correlation with large tumor size, high mitosis, and high NPI score." (PMID 38195458, 2024). "This suggests that KIF18A could be a promising synthetic lethal candidate for future drug development efforts targeting tumor cells with CIN." (PMID 38553459, 2024). "Furthermore, there was a significant direct correlation between high KIF18A H score value and large tumor size (p<0.001), high mitosis (p<0.012), and high NPI score (p<0.001)." (PMID 38195458, 2024). "This potential graded phenotypic response following partial and more complete inhibition of KIF18A is useful to consider when evaluating whether KIF18A inhibitors produce effects that may potentially inhibit CIN tumor proliferation." (PMID 38410188, 2024). "KIF18A is found overexpressed in a wide variety of tumors, and promotes carcinogenesis, therefore KIF18A overexpression might provide a window for tetraploidy tolerance and further tumor progression." (PMID 37342233, 2023). "Subsequently, we explored KIF18A gene alterations in different tumor tissues using cBioPortal." (PMID 36830695, 2023). "Furthermore, KIF18A S284 mutants display loss of KIF18A function and fail to support proliferation in CIN tumor cells." (PMID 37905069, 2023). "Thus, KIF18A can abrogate the inhibitory effects of miR-30b-5p on cell growth, metastasis and autophagy, suggesting that KIF18A also plays a pro-tumor role in irradiation-tolerant PCa cells." (PMID 36358938, 2022). "In our study, analysis of data acquired from the CCLE database revealed the potential therapeutic target significance of KIF18A, that was, inhibiting its expression or function could inhibit tumor growth." (PMID 35677036, 2022). "There was no obvious difference between high and low KIF18A groups in other clinical features, including patient age, gender, tumor lateralization, and IDH1 mutations." (PMID 35464837, 2022). "In conclusion, patients with high expression of KIF18A tend to have more inhibitory immune cell infiltration, and KIF18A may play an important role in the construction of a tumour-suppressive immune microenvironment." (PMID 35591854, 2022). "Tumor samples were divided into two groups according to the expression of KIF18A." (PMID 35464837, 2022). "Recently, an increasing number of scholars have paid attention to the role of KIF18A in tumours, in order to investigate the mechanism of involvement of KIF18A in tumour genesis, development, and evolution, and to provide a basis for KIF18A as a molecular target for tumour therapy." (PMID 35591854, 2022). "Taken together, we speculate that the abnormal increase in Th2 cells in the tumour microenvironment might be one of the crucial factors for the poor prognosis of patients with high expression of KIF18A." (PMID 35591854, 2022). "In addition, the expression level of KIF18A increased with an increase in tumour grade, and the highest expression level of KIF18A was found in grade 4, the highest degree of malignancy." (PMID 35591854, 2022). "To know more about the role of KIF18A in neoplasms, we studied two other proteins: Ki67 and PCNA." (PMID 35464837, 2022). "We subsequently detected the expression levels of KIF18A in tumor tissues through IHC assays." (PMID 35464837, 2022). "The possible effect of KIF18A on GBM tumor growth was determined in mice." (PMID 35464837, 2022). "The result showed that when KIF18A was highly expressed, tumor formation was induced." (PMID 35464837, 2022). "In addition, many researchers have reported that KIF18A is a potential therapeutic target and prognostic factor for a variety of tumours, including hepatocellular carcinoma, prostate cancer, and lung adenocarcinoma." (PMID 35591854, 2022).